CDK4 (cyclin dependent kinase 4)
Diseases named in the same sentence as CDK4 in open-access papers (continued):
Sharing a sentence is not in itself a finding about the gene and the disease.
breast cancer (continued). "Thus, MITF appears to play an important role in regulating palbociclib resistance in CDK4/6i resistant breast cancer cells." (PMID 37886470, 2023). "The addition of CDK4/6 inhibitors (CDK4/6is) to endocrine therapy (ET) has greatly improved outcomes for patients with hormone receptor–positive (HR+)/human epidermal growth factor receptor 2–negative (HER2−) advanced breast cancer (ABC)." (PMID 37653397, 2023). "Targeting CDK4/6 has demonstrated promising effects against breast cancer." (PMID 37886470, 2023). "Recently, multiple CDK4/6 inhibitors have been approved for the treatment of breast cancer." (PMID 36670542, 2023). "We aimed to reveal the mechanism of CPVL in breast cancer resistance to CDK4/6 inhibitors." (PMID 36825764, 2023). "In summary, we revealed the effects of CPVL on resistance to CDK4/6 inhibitors in breast cancer." (PMID 36825764, 2023). "Nowadays, the upfront treatment for patients facing a diagnosis of advanced luminal breast cancer (BC) is a combination of endocrine therapy (ET) with an inhibitor of CDK4/6 (CDK4/6i), which effectively targets and prevents cell cycle progression in hormone-dependent BC." (PMID 37835528, 2023). "Some studies have shown that PPI use may be associated with decreased progression-free survival and overall survival in breast cancer patients treated with CDK4/6 inhibitors." (PMID 36994248, 2023). "Moreover, since cyclin D1 is downstream of HER2 signaling, CDK4/6 inhibitors can enhance the therapeutic effect on HER2-positive breast cancer." (PMID 38352694, 2023). "Taken together, these data indicate that RMC-6272 may be an effective therapeutic option to overcome CDK4/6 inhibitor resistance in breast cancer." (PMID 37264081, 2023). "Palbociclib is the first marketed cell CDK4/6 inhibitor that exerts its antitumor effects by inhibiting the binding of CDK4/6 and cell cycle protein D, interfering with retinoblastoma protein (RB) phosphorylation, and reducing cell proliferation in breast cancer cell lines." (PMID 36998437, 2023). "To investigate the type, strength, and mechanism of cell interactions in heterogeneous cancer populations during treatment, we use ER+ breast cancer cell lineages that are sensitive or resistant to a CDK4/6 cell cycle inhibitor (ribociclib), a standard therapy used to treat this cancer." (PMID 37386030, 2023). "When WEE1 is targeted, it inhibits the growth of CDK4/6i-resistant breast cancer cells." (PMID 37475713, 2023). "The results of this study and similar studies may provide substantial insight into potential therapeutic strategies by targeting the Hsp90-ATF2 and CDK4/6 pathways in breast cancers." (PMID 37955015, 2023). "The drug response test using PDOs further validated that high MITH was an indicator for CDK4/6 inhibitor resistance in HR+ breast cancers and CDK2/4/6 inhibitor may be an effective option for the patients with high-MITH HR+ breast cancer." (PMID 37880211, 2023). "The combination of ET with a CDK4/6 inhibitor is the standard of care first line treatment for advanced ER+/HER2-breast cancer, and while practice changing and improving survival outcomes, patients eventually develop progressive disease due to intrinsic or acquired drug resistance." (PMID 37035239, 2023). "With the CDK4/6 inhibitor palbociclib approved for the treatment of breast cancer and inhibitors of other CDKs that exhibit antiproliferative effects at various stages of preclinical and clinical testing, therapeutic interest in this family of serine‐threonine kinases is growing." (PMID 36855776, 2023). "Abemaciclib is the only CDK4/6 inhibitor approved for breast cancer treatment as monotherapy." (PMID 37234717, 2023). "To evaluate the association of each ctDNA-based signatures with patient’s outcome, we analyzed baseline pre-treatment plasma samples from 124 patients with advanced HR+/HER2- breast cancer treated with endocrine therapy and a CDK4/6 inhibitor (CDK-Validation-1 cohort)." (PMID 36859416, 2023).
breast cancer (continued). "Palbociclib is a CDK4/6 inhibitor that inhibits growth of Rb-intact breast cancer xenografts." (PMID 37298855, 2023). "In addition, upregulation of transcription factor YB-1 also occurred in CDK4/6i-resistant breast cancer, and YB-1 inhibition can regulate PARP1 expression." (PMID 38037159, 2023). "Endocrine therapies comprise different classes, among which are selective estrogen receptor degraders (SERDs), such as fulvestrant, which in combination with CDK4/6 inhibitors, including palbociclib, is one of the standard care therapies for metastatic ER-positive/Her2-negative breast cancer." (PMID 37627092, 2023). "Besides breast cancer, CDK4/6 inhibitors have been shown as a promising therapy for several other cancers, including glioma, multiple myeloma, and liposarcoma, and are currently being evaluated for a variety of other cancers." (PMID 36765923, 2023). "Moreover, the combination of CDK4/6 inhibitor and endocrine therapy has emerged as the frontline therapy for HR-positive breast cancer patients." (PMID 38068930, 2023). "As in vitro models of cellular senescence, AGS cells (derived from a human gastric adenocarcinoma) and MCF-7 cells (derived from a human mammary carcinoma) were exposed for 96 h to Palbociclib, a targeted drug that induces cellular senescence as a result of the inhibition of CDK4/6 kinases." (PMID 37298236, 2023). "In addition, CDK4 knockdown inhibits the onset and incidence of mammary carcinoma in MMTV‐Neu‐Cdk4−/− mice." (PMID 37279947, 2023). "Lastly, as CDK4/6 inhibitors in combination with ET are approved for use in first‐line HR+, HER2− advanced breast cancer, some may question the applicability of our findings for a CDK4/6 inhibitor‐treated patient population." (PMID 36892268, 2023). "Biomarkers for CDK4/6 inhibitors have been thoroughly investigated through molecular profiling of tumor material, but to date, the only clinically available biomarker remains breast cancer subtype as defined by traditional tissue markers (i.e., ER+/HER2-)." (PMID 36176758, 2022). "Although CDK4 overexpression has been seen in several cancers and may limit the therapeutic efficacy of CDK4/6Is, this is an uncommon event in breast cancer." (PMID 36358806, 2022). "Dual targeting of BCL2 and CDK4/6 has shown good activity in ER + breast cancer, and so choriocarcinoma patients with intrinsically lower tumour expression for BCL2 may be particularly responsive to treatment with Palbociclib." (PMID 35301407, 2022). "Furthermore, the CDK4/6 inhibitor abemaciclib enhances the efficacy of anti-PD-L1 ICIs by augmenting antigen presentation and T cell activation in human breast cancer cells." (PMID 36387071, 2022). "Editing breast cancer tissue with anti-estrogen therapies provides the possibility to enhance pro-apoptotic processes by blocking the frequently occurring up-regulation of cyclin D1 in breast cancer cells with CDK4/6 inhibitors." (PMID 35814409, 2022). "Abemaciclib, a CDK4 & 6 inhibitor, is indicated for advanced breast cancer treatment." (PMID 35915198, 2022). "Investigations in breast cancer samples have shown up-regulation of CDK4/6 in different subtypes." (PMID 36266723, 2022). "Moreover, the link between high levels of CDK4 and endocrine resistance within breast cancer cells has been identified." (PMID 35764927, 2022). "Moreover, to date, abemaciclib is the first FDA-approved CDK4 & 6i approved for the adjuvant treatment of HR+, HER2–, node-positive, early breast cancer (EBC) at high risk of recurrence and a Ki-67 score ≥20%." (PMID 35813283, 2022). "CCND1 amplification can predict sensitivity to CDK4/6 inhibitors such as abemaciclib, palbociclib, and ribociclib, although these agents have reported only limited efficacy as monotherapy in tumor types other than breast cancer." (PMID 35884537, 2022).
breast cancer (continued). "However, intrinsic or acquired resistance of HR+/HER2- metastatic breast cancer to clinically approved CDK4/6 inhibitors are responsible for disease progression in the majority of patients." (PMID 35938171, 2022). "However, intrinsic or acquired resistance to clinically approved CDK4/6 inhibitors have emerged as a major obstacle that hinders their utility in breast cancers." (PMID 35756622, 2022). "Thus, CDK4/6 inhibitors achieved broad clinical applications in the current breast cancer treatments." (PMID 35756622, 2022). "Mechanisms of breast cancer cell escape from CDK4/6 inhibitors involves intrinsic and acquired resistance and the mechanisms of resistance to the various CDK4/6 inhibitors may differ." (PMID 36077830, 2022). "ER+ breast cancer is highly reliant on an intact cyclin D-CDK4/6-Rb axis, as estrogen drives cyclin D1 expression leading to the formation of the cyclin D-CDK4/6 complex, ultimately inducing cell proliferation through the CDK4/6 pathway." (PMID 36176758, 2022). "It will be important in the future to measure replication stress directly in breast cancer patients treated with CDK4/6 inhibitors, and to compare this in patients who are dosed continuously, as with abemaciclib, or in repeated on/off cycles, as with palbociclib/ribociclib." (PMID 35037284, 2022). "Supporting this are observation that high Cyclin D1 expression levels correlate with long-term prognosis in ILC, and the finding that the CDK4/6 inhibitor abemaciclib induces upregulation of Cyclin D1 in luminal-type ER+ and lobular-type breast cancer cell lines." (PMID 35437308, 2022). "To examine whether abemaciclib altered CDK4 T172 phosphorylation we treated T47D breast cancer cells for 4 or 24 h with CDK4/6i and quantified CDK4 T172 phosphorylation by LC-MS/MS." (PMID 36446794, 2022). "The cell cycle pathway is a key pathway in ER+ breast cancer and the target of CDK4/6 inhibitors." (PMID 35740538, 2022). "Finally, to validate these findings in a clinically relevant system, we measured the NASP in breast cancer patients prior to and after treatment with either chemotherapy or CDK4/6i." (PMID 34985783, 2022). "Likewise, we previously reported the protective role of cytoplasmic p21 in the apoptosis of CDK4/6 inhibitor‐induced senescent breast cancer cells." (PMID 36054146, 2022). "This hypothesis was supported by a study in breast cancer cells that proposed the role of INK4 proteins in palbociclib binding to CDK4/6." (PMID 35326705, 2022). "This review focuses on the recent resistance mechanisms identified and potential therapeutic targets for conventional and combination endocrine therapies with CDK4/6 inhibitors by various breast cancer clinical trials and research groups in HER amplified and/or mutated breast cancer tumour." (PMID 35800379, 2022). "In xenograft models of breast cancer, CDK4/6 inhibitors could reduce proliferation, and enhance anti-tumor immune responses." (PMID 36266723, 2022). "Finally, CDK4/6 amplification or overexpression has also been observed in a wide spectrum of tumors, including gliomas, sarcomas, lymphomas, melanomas, cancers of the breast, squamous cell carcinomas and leukemias [reviewed in 118, 123]." (PMID 36051751, 2022). "Expert panel recommendations: With combination therapy of CDK4/6 inhibitors plus endocrine therapy becoming the first‐line treatment of HR‐positive/HER2‐negative advanced breast cancer now, in general, CDK4/6 inhibitor plus fulvestrant is also administered in patients who failed AI therapy." (PMID 38089455, 2022). "As one might expect given their mechanism of action, CDK4/6 inhibitors induce cytostasis (G1 cell cycle arrest) in RB-proficient luminal breast cancer cells in vitro." (PMID 35248122, 2022). "In addition to clinical trials for breast cancer, the three CDK4/6 inhibitors underwent and are still undergoing testing in several clinical trials for other types of cancer, both as a single drug and in combination therapy." (PMID 35892870, 2022).
breast cancer (continued). "This strategy was based on a clear synergy between anti-HER2 therapy and CDK4/6 inhibitors in HER2+ breast cancer cell lines and the demonstration in transgenic mice that the activation of cyclin D1–CDK4/6 was involved in mediating resistance to anti-HER2 therapy." (PMID 36466034, 2022). "This has led to the clinical development of endocrine-based combination therapies such as the SERD, fulvestrant, together with the cyclin dependent kinase 4/6 (CDK4/6) inhibitor palbociclib/PD-0332991, which collectively prolong survival of patients with advanced ER+ breast cancer." (PMID 36612130, 2022). "Thus, targeted drug design for the treatment of breast cancer with CDK4/6 as a target has important potential." (PMID 36744210, 2022). "Taken together, these data point to the potential for overcoming resistance to CDK4/6 inhibition via drugs targeting alternate signaling pathways, and to the utility of the mammary cancer models presented here for evaluation of therapeutic combinations that target these pathways." (PMID 36333737, 2022). "Thus, after decades of endocrine therapy as a single agent the approval of everolimus, alpelisib, and CDK4/6 inhibitors has led to significant progress in breast cancer management." (PMID 35774123, 2022). "Therefore, biomarkers are urgently needed to predict CDK4/6 inhibitor efficacy or resistance in metastatic breast cancer patients, allowing clinicians to tailor treatment and potentially add additional therapies for patients at high risk of early progression." (PMID 36176758, 2022). "However, translating the success of CDK4/6 inhibitors from HR+ breast cancer to other cancer types has been hampered by intrinsic resistance." (PMID 36067171, 2022). "Their success is reflected in clinical approvals of specific CDK4/6 inhibitors for breast cancer." (PMID 35053461, 2022). "Hormone therapy using selective oestrogen receptor modular (SERMs) or selective oestrogen receptor degraders (SERDs) is the first line treatment for ER + breast cancers, however combination with CDK4/6 inhibitor (i.e. Palbociclib) has significantly improved clinical outcome of advanced BC patients." (PMID 35217640, 2022). "The sequential combination of abemaciclib following eribulin could be an effective treatment strategy in overcoming resistance to CDK4/6 inhibitors in HR-positive breast cancer." (PMID 35008374, 2022). "In HR+ advanced breast cancer, upregulated exosomal mRNAs encoding cell cycle-regulated thymidine kinase 1 (TK1) (p = 0.01) and cyclin-dependent kinase 9 (CDK9) (p = 0.03) correlated with poor clinical response to the CDK4/CDK6 inhibitor palbociclib." (PMID 35565189, 2022). "Circumventing the spatial and temporal limitations of tissue biopsy, newly developed liquid biopsy approaches have the potential to uncover biomarkers that can predict CDK4/6 inhibitor efficacy and resistance in breast cancer patients through a simple blood test." (PMID 36176758, 2022). "CDK4/6I-resistant breast cancer cell lines show reactivation of phosphorylated-Rb and E2F, which may occur via the CDK or the mTOR pathways." (PMID 36358806, 2022). "In contrast to CDK4/6 inhibitor–mediated radiosensitization in breast cancer that is primarily mediated through suppression of HR, inhibition of other CDK proteins leads to increased apoptosis, senescence, and/or inhibition of RNA Polymerase II function that leads to radiosenstization." (PMID 34932500, 2022). "We found that the correlations of sensitivity to the CDK4/6 inhibitors palbociclib and ribociclib with ENST00000547281 were significantly stronger than the correlations of sensitivity to the CDK4/6 inhibitors palbociclib and ribociclib with the CDK4 gene in breast cancer." (PMID 36529792, 2022). "This is somehow intriguing, as RAS G12V has not been associated with resistance against CDK4/CDK6 inhibitors in the context of breast cancer or other malignancies." (PMID 35804842, 2022).
breast cancer (continued). "If this is a mechanism of resistance, the ability of the lysosome to sequester CDK4/6 inhibitors may be breast cancer cell and/or context dependent." (PMID 36077830, 2022). "However, since their approval, clinical evidences have demonstrated that about 30% of breast cancer is intrinsically resistant to CDK4/6 inhibitors and that prolonged treatment eventually leads to acquired resistance in many patients." (PMID 35712501, 2022). "Similarly, CDK4/6 inhibition induces RB-dependent chromatin accessibility changes in breast cancer cell lines that are reliant on time." (PMID 35019938, 2022). "Similar questions arise regarding the use of adjuvant CDK4/6 inhibitors in ERlo breast cancer." (PMID 36506043, 2022). "Breast cancers with S6K1 amplification could be considered for combinations of CDK4/6 and S6K1 antagonists." (PMID 36042494, 2022). "Consequently, sustained binding of abemaciclib to CDK4 leads to potent cell cycle inhibition in breast cancer cell lines and prevents rebound activation of downstream signaling." (PMID 36446794, 2022). "Acquired resistance to CDK4/6 inhibitors occurs in highly responsive HR‐positive breast cancer." (PMID 36065138, 2022). "This possible impact on ALR may lead to an increase in lysosome concentration in cancer cells, which has been shown to induce acquired resistance to the CDK4/6 inhibitor in breast cancer." (PMID 36010871, 2022). "CDK4/6 inhibitors, commonly applied to treat breast cancer, are small molecule inhibitors that competitive binding ATP, which inhibit CDK4/6 from forming a complex with Cyclin D and block ATP binding, hence cutting off upstream growth signals and preventing the G1 to S phase transition of cells." (PMID 36612173, 2022). "Nonetheless, since the incidence of RB gene deletion/mutation is rare in ER+ breast cancer, it thus does not explain the high prevalence of disease recurrence on CDK4/6 inhibitors." (PMID 35740538, 2022). "Considering gene signature assays can become routine in the clinical management of ER+ breast cancer patients, such as MammaPrint and OncotypeDx, specific gene signatures that are predictive of therapy with CDK4/6 inhibitors may be defined and developed." (PMID 36176758, 2022). "An article published in 2019 proved that CDK4/6 inhibitors, approved for a breast cancer subtype, could be used to treat SCCOHT." (PMID 35200537, 2022). "Given that early cell cycle events are mainly executed by Cdk4/6, in-depth mammalian studies may also have relevance for human disease, because Cdk4/6 inhibitors have gained attraction in the treatment of various forms of cancer, particularly breast cancer." (PMID 35163213, 2022). "Consequently, the authors demonstrated that treatment of breast cancer cells with cdk4/6 inhibitors promoted the degradation of Rb." (PMID 36091143, 2022). "In a genomic analysis of breast cancers that were resistant to CDK4/6 inhibitors, loss-of-function mutations were found in the FAT1 gene, and the knockout of FAT1 conferred resistance to CDK4/6 inhibitors by the overexpression of the CDK6 protein via the suppression of the Hippo pathway." (PMID 35681048, 2022). "The development of resistance to CDK4/6 inhibitors from both the pre-activation of the PI3K or MAPK pathway or compensatory activation is being explored extensively in breast cancer, and clearly warrants preclinical testing in pediatric and AYA sarcomas with CDK4/6 hyperactivation." (PMID 35892870, 2022). "Intriguingly, in breast cancer biopsies, the immunohistochemical expression of both total p27 and its pY88 form stratified the tumor sensitivity to Palbociclib, supporting the correlation between pY88-p27, CDK4 activity and Palbociclib sensitivity." (PMID 35712501, 2022). "Multiple mechanisms of resistance to CDK4/6 inhibitors activate the MAPK pathway in HR + metastatic breast cancer cells, thus the sensitivity of our model to MEK inhibition may be extended to additional agents that target the MAPK pathway." (PMID 36333737, 2022).